MIR485 (microRNA 485)
Synonyms: hsa-mir-485; MIRN485; mir-485
Gene: MicroRNA gene on chromosome 14 (101,055,419 to 101,055,491, forward strand). Ensembl gene ENSG00000208027.
Gene Ontology:
Biological process: miRNA-mediated post-transcriptional gene silencing
Cellular component: RISC complex
Homologues: Orthologues: chimpanzee ptr-mir-485 (100% identical).